KLF4 (KLF transcription factor 4)
Diseases named in the same sentence as KLF4 in open-access papers (continued):
Sharing a sentence is not in itself a finding about the gene and the disease.
tumor (continued). "Moreover, the anti-tumor activity of APTO253 was attributed to the induction of KLF4, which is often down-regulated in hematological cancers." (PMID 37143070, 2023). "Importantly, KLF4 inhibited tumor growth by regulating the typical cyclin regulatory molecules, p21 and cyclinD1." (PMID 37031197, 2023). "Depending on the cell type, KLF4 acts as both a tumour suppressor and an oncogene." (PMID 37559082, 2023). "KLF4 expression varies by cancer type, and during carcinogenesis, it may be tumor-suppressive or oncogenic, depending on the tumor stage." (PMID 37176108, 2023). "Interestingly, KLF4 can also maintain cancer cells’ stemness and mesenchymal properties and promote cell proliferation in specific microenvironments and tumor types." (PMID 36761967, 2023). "KLF4 may be involved in tumor development through the WNT5A signaling pathway, a WNT pathway activated by the receptor tyrosine kinase ROR2." (PMID 36761967, 2023). "Taken together, KLF4 might exert its role as a tumor suppressor through various mechanisms by preventing epigenetic modifications via directly blocking protein activity, suppressing mutagenesis, and regulating DNA damage repair." (PMID 37173904, 2023). "Krüppel-like factor 4 (KLF4) has been postulated to be a tumor suppressor of HCC." (PMID 36834633, 2023). "While tumor burden did increase over time for both conditions, this could be representative of cells within the pool of KLF4 knockout cells that escaped editing of the KLF4 locus." (PMID 37938582, 2023). "KLF4 knockdown cells also exhibited decreased tumor formation." (PMID 37886981, 2023). "Thus, the role of KLF4 as an oncogene or tumor suppressor is dependent on the status of other proteins such as p21CIP1, the cancer type, and the developmental stage." (PMID 37760529, 2023). "Tumor tissues exhibited 46.1%, 47.52%, and 6.38%, whereas normal tissues exhibited 31.21% in the moderate group and 68.79% in the strong group, indicating that KLF4 expression was lower in tumors than in normal tissues." (PMID 36936440, 2023). "KLF4 is a cell cycle-blocking factor in tumor tissues such as PC and BC." (PMID 36761967, 2023). "Taken together, DYRK2 as a tumor suppressor may regulate cell stemness and tumor formation through an inhibitory interaction with KLF4." (PMID 37886981, 2023). "Monomethyltransferase SET8 can directly inactivate KLF4 and promote tumor progression." (PMID 37031197, 2023). "KLF4 has been shown to function as a tumor suppressor or oncogene in cell-dependent contexts." (PMID 37143070, 2023). "Further studies are needed to determine whether KLF4 is enriched in tumor exosomes and whether exosomal KLF4 can be used for clinical diagnosis and therapy." (PMID 37031197, 2023). "Hence, circ_0020256 drove transplanted tumor growth in the nude mice by modulating EIF4A3/KLF4 pathway." (PMID 37179359, 2023). "Our prognostic model incorporating KLF4 expression, tumor differentiation, and TNM stage showed better accuracy than TNM stage alone, which may enable clinicians to make more cost-effective follow-up program and precise treatment decisions for the patients." (PMID 36936440, 2023). "The aberrant expression of CDC42 is strongly associated with the development of a variety of tumors, and thus, it may be a downstream product of KLF4 involvement in tumor progression." (PMID 36761967, 2023). "KLF-4 is a transcription factor with anti-proliferative effects in differentiated cells; in PC malignancies it acts as a tumor suppressor by upregulating p21CIP and downregulating c-Myc and cyclin D2 and is also associated with melphalan and carfilzomib drug resistance." (PMID 36752202, 2023). "As a tumor-suppressor molecule, KLF4 has been identified in gastrointestinal cancers." (PMID 36936440, 2023).
tumor (continued). "Herein, we performed immunofluorescence staining of KLF4 in tumor tissues from patients." (PMID 37809806, 2023). "For instance, HCC with low KLF4 expression, tumor stage III, and tumor differentiation grade I/II would have a total of 191 points (91 for KLF4 expression, 0 for tumor differentiation grade I/II, and 100 for tumor stage III), corresponding to a predicted 1-year OS of 42.0%." (PMID 36936440, 2023). "Therefore, the function of KLF4 in tumorigenesis is highly complex, given the context of different tumor subtypes, diverse molecular regulation and malignancy of tumor cells." (PMID 37031197, 2023). "However, it is also tempting to use KLF4 as a biomarker for tumor diagnosis and prognosis, which must be in conjunction with the knowledge of physiology, pathology, and imaging data for specific types/subtypes of tumors." (PMID 37031197, 2023). "KLF4 functions either as a tumor suppressor or as an oncogene in a tissue-specific fashion." (PMID 37835497, 2023). "In different cell types, KLF4 functions as both a tumour suppressor and an oncogene." (PMID 37559082, 2023). "Moreover, CSCs can stabilize KLF4 expression by promoting the deubiquitinating process of KLF4 and further enhance CSC-associated tumor metastasis." (PMID 37853437, 2023). "The inconsistent roles of KLF4 in tumor development and progression may be due to multiple factors, including the types of tumors, stage of tumor progression, isomers and their regulation." (PMID 37031197, 2023). "The formation of this complex promotes the translation of the oncogene mRNA, causing cancer cells to acquire increased malignant tumor-forming capacity in vivo and increased protein levels of pluripotency factors OCT4, SOX2, NANOG and KLF4 (Kruppel-like factor 4)." (PMID 35954194, 2022). "Many studies have shown that KLF4 has various mechanisms in different tumours; however, the prognostic role of KLF4 remains unclear." (PMID 35177016, 2022). "In vivo experiments also showed that deguelin could upregulate the expression of PTEN and KLF4 in tumor-bearing mice and then significantly inhibit the growth of NSCLC in mice." (PMID 35637651, 2022). "Collectively, these findings indicate that KLF4 might play a tumour suppressing role in STAD by regulating HADHB expression and modulating its downstream gene expression, such as proliferation- or metastasis-associated genes." (PMID 36518312, 2022). "Collectively, these findings imply that KLF4 might play a tumour suppressing role in STAD by interacting with the HADHB promoter at the 361-371 site to regulate its expression." (PMID 36518312, 2022). "KLF4 hypermethylation was observed in 6 of the overall included 35 samples (17.1%); however, there was no statistically significant relation of the methylation status with tumor subtype, histological grade or age group." (PMID 34854470, 2022). "Furthermore, the overexpression of KLF4 was noted to weaken the anti-tumour effects of CHRM3-AS2 silencing both in vitro and in vivo." (PMID 35359381, 2022). "MiR-135b-5p was notably increased in cancer cells, and overexpressing KLF4 functioned a tumor repressive role, which could be restored by miR-135b-5p." (PMID 35027543, 2022). "In the context of the tumor microenvironment, tumor-derived SHH executes immunosuppressive and tumor-supporting functions by promoting Krüppel-like factor 4 (KLF4)-mediated polarization of M2 tumor-associated macrophages (TAMs) and upregulation of PD-L1 expression in TAMs." (PMID 35464958, 2022). "Moreover, we compared the expression of each TCFL5 exon with that of SOX2 and KLF4 in tumour samples." (PMID 34623757, 2022).
tumor (continued). "KLF-4 can also act as a tumor suppressor depending on the localization." (PMID 35269992, 2022). "KLF4 plays a tumor suppressor role in gastrointestinal tumors but it promotes HCC progression." (PMID 35093082, 2022). "Furthermore, the tumor suppressor KLF4 decreases tumor invasion by downregulating the expression of SPARC." (PMID 35981080, 2022). "In addition, sh-CHRM3-AS2-induced down-regulation of KLF4 expression was reversed by the intervention of oe-KLF4 in tumour xenografts (P < 0.001)." (PMID 35359381, 2022). "On the other hand, KLF4 is considered a tumour suppressor gene." (PMID 34623757, 2022). "MiR-135b-5p and GPRC5A were conspicuously decreased in the tumor tissue of miR-135b-5p antagomir+Ad-NC group, and the expression of KLF4 was higher than NC group, while GPRC5A level in the miR-135b-5p antagomir+Ad-GPRC5A group was markedly higher than that in the other 2 groups." (PMID 35027543, 2022). "KLF4 is a transcription factor that is widely present in eukaryotic cells with zinc finger structures and can promote cancer or tumour suppressors in different types of tumours." (PMID 35177016, 2022). "The results indicate that knockdown of KLF4 prevents tumor metastasis of NSCLC in vivo." (PMID 35982899, 2022). "Congruently, the genes upregulated in tumor-draining LN fLECs, including several transcription factors that regulate lymphatic differentiation and lymphangiogenesis (Prox1, Klf4, Sox7, and Yap1), were significantly enriched for proliferation-, migration-, and angiogenesis-related GO terms." (PMID 35892863, 2022). "Targeting the KLF4-Rictor axis may be a promising anti-tumor strategy to overcome metastasis in NSCLC." (PMID 35982899, 2022). "Interestingly, TUG1-deficient mice demonstrated high and low expressions of E-cadherin along with N-cadherin as tumor metastasis-correlated EMT markers exerting the TUG1/miR-153-1/KLF4 axis in in vivo EMT of CRC cells." (PMID 36333703, 2022). "KLF4 upregulation abolished the HADHB knockdown-induced tumour promoting effects in AGS cells." (PMID 36518312, 2022). "Knockdown of KLF4 prevents mTOR/Rictor interaction and tumor metastasis of NSCLC in vivo." (PMID 35982899, 2022). "KLF4 hypermethylation was observed in six of the overall included thirty-five samples (17.1%), however, there was no statistically significant relation of the methylation status with tumor subtype, grade or age group." (PMID 34854470, 2022). "The results of qRT-PCR are consistent with those of bioinformatics analysis, meaning that SLC2A1 may be an oncogene in LUAD, while KLF4 may be a tumor suppressor gene." (PMID 35711943, 2022). "Overexpression of KLF4 also weakened the anti-tumour effect of CHRM3-AS2 silencing in mice." (PMID 35359381, 2022). "Conversely, KLF4 inhibitor Kenpaullone promoted tumor organoid growth." (PMID 36276637, 2022). "However, by Sanger sequencing, we did not detect mutations at the established hotspots in AKT1, SMO, KLF4 and TRAF7, suggesting different tumor drivers acting in this age group." (PMID 34495383, 2021). "Moreover, with the decrease in H3K4me1 level at enhancers, transcription factors such as LIFR and KLF4 were markedly downregulated, effectively inhibiting tumor progression." (PMID 34758724, 2021). "However further experimental studies would be required in order to clarify the biological role of PGRMC1 in tumor stemness associated pathway, such as OCT3/SOX2/NANOG/KLF4." (PMID 34746100, 2021). "It is important to note that few studies have reported Klf4 to be a tumor promoting factor." (PMID 34195082, 2021). "Overexpressing SF3B4 resulted in a mis-splicing of Kruppel-like factor 4 (KLF4), a tumor suppressor-encoding gene, into a non-functional transcript in cancer cells, and thus promoting tumorigenesis in HCC." (PMID 33563334, 2021). "Nevertheless increased KLF4 expression, we detected in senescent cells still can have important implications in tumorigenesis and therapy response through inducing dedifferentiation of tumor cells." (PMID 33524223, 2021).
tumor (continued). "KLF4 is involved in the regulation of numerous biological processes including cell development and cell division, apoptosis, and cell programming, and its down-regulation is often coupled with tumor progression." (PMID 34707153, 2021). "Since we found that KLF4 acts as a tumor suppressor with respect to inducing cell death following glucose starvation, we decided to investigate whether KLF4 has any other tumor-suppressing roles in response to glucose starvation." (PMID 33917010, 2021). "Furthermore, the targeting of BMI1 or KLF4 has been demonstrated to benefit cancer patients or inhibit tumor progression in preclinical studies." (PMID 33828977, 2021). "However, tumor suppressive and oncogenic functions of KLF4 are cell type, context, and subcellular localization dependent, but how KLF4 exert these differential functions and the associated molecular mechanisms remains unraveled." (PMID 34440860, 2021). "However, in colon and gastric carcinoma cells, KLF4 has p21Cip1-dependent tumor suppression activity, thus inhibiting tumor progression and carcinogenesis." (PMID 34488885, 2021). "This is because KLF4α is highly expressed in A549 cells, which may have masked the KLF4 (FL) from nuclear translocation and exert its tumor suppressing effects." (PMID 34440860, 2021). "In summary, PiHL is induced by KLF4 downregulation and confers chemoresistance to tumor cells." (PMID 33986248, 2021). "MiR-18a is overexpressed in HCC and targets KLF4 to promote tumor metastasis and growth in HCC." (PMID 34187598, 2021). "Krüppel-like factor 4 (KLF4) can inhibit the development of tumor by associating with the non-Warburg metabolic behaviors." (PMID 34603375, 2021). "KLF4 has been shown to function as a tumor-promoting factor in many cancers." (PMID 33918002, 2021). "For example, in liver carcinoma and osteosarcoma, KLF4 has been linked to transforming non-CSCs into tumor cells with enhanced stem-cell marker expression, and metastatic capacity." (PMID 34638302, 2021). "Similarly, KLF4 expression was also found to be decreased in tumor tissue in the HCC tissue microarray and its low expression predicted advanced progression." (PMID 32350244, 2020). "Moreover, Klf4, characterized as a novel tumor suppressor in multiple tumor types, is significantly decreased, indicating that CD4 TCM cells are susceptible to cell death in aged mice." (PMID 33644036, 2020). "Besides being associated with normal cell functions such as growth, differentiation, and apoptosis, KLF4 also functions as either an oncogene or a tumor suppressor, depending on the cellular context, through interaction with different target genes." (PMID 33240028, 2020). "In our study we show that by leveraging the mTor dependency of HIF1-α, Temsirolimus suppresses the overshooting hypoxia response, reduces VEGF levels under normoxic and hypoxic conditions and inhibits tumor growth both in vitro and in vivo in KLF4-overexpressing tumor cells." (PMID 32245394, 2020). "In summary, our findings have identified CD9 and CD81 as potential tumor suppressor genes in HCC, which may mediate KLF4-induced suppression of tumor cell growth via JNK signaling for the first time." (PMID 32350244, 2020). "KLF4 displays a tumor-suppressive function, which is downregulated in CRC." (PMID 33224957, 2020). "KLF4 positively regulates the expression of P-cadherin, which acts as a tumor suppressor in HCC." (PMID 33266506, 2020). "KLF4, a well-known Yamanaka factor, is a complex transcription factor that, depending on the context, can act as a transcriptional activator, a transcriptional repressor, an oncogene or a tumor suppressor." (PMID 32408542, 2020). "Also, aggressive tumor phenotypes such as advanced BCLC stages, high levels of AFP, present vascular invasion and poor differentiation were associated with low KLF4 expression." (PMID 32756012, 2020). "The results of most studies suggest that KLF4 is a tumor suppressor." (PMID 33266506, 2020).
tumor (continued). "In humans, overexpressing SF3b4 resulted in a mis-splicing of Kruppel-like factor 4 (KLF4), a tumor suppressor-encoding gene, into a non-functional transcript in cancer cells, and thus promoting tumorigenesis in HCC." (PMID 32083075, 2020). "KLF4 thus blocks the malignant transformation and impedes tumor progression." (PMID 33266506, 2020). "Therefore the involvement of KLF4 in cancer development is not limited to cancer cells, but it is very important in the tumor microenvironment as well." (PMID 33266506, 2020). "Moreover, KLF4 regulates blood-tumor barrier permeability by altering the expressions of tight junction-related proteins." (PMID 32264912, 2020). "Thus, KLF4 can act as a tumor suppressor or oncogene in different cancer types, largely depending on the cellular context, chromatin structure, cell cycle regulation, and expression patterns of other genes, including specific oncogenic drivers." (PMID 32156068, 2020). "Moreover, in vivo analyses have shown that KLF4 suppresses tumorigenicity and inhibits primary tumor growth and metastases in xenograft models." (PMID 32552913, 2020). "The relationship between some specific microRNAs and KLF4 in these neoplasms is also well known." (PMID 33266506, 2020). "Clinically, KLF4 expression in the primary tumor does significantly influence survival." (PMID 32429174, 2020). "KLF4 is downregulated in numerous cancers but upregulated in others, and abnormal KLF4 expression might reflect oncogenic or tumor suppressor functions depending on the cellular context, tumor type, subtype and stage." (PMID 32944247, 2020). "Notably, Klf4 has been shown to be down-regulated during tumor initiation and consecutively lost during GC progression." (PMID 33023180, 2020). "In cervical carcinoma, KLF4 as a tumor suppressor inhibited cell growth and tumor formation." (PMID 32756012, 2020). "In this way, KLF4 may be considered to act not only as a tumor suppressor, but more broadly, as a critical “cell stability molecule”, and an important maintainer of tissue homeostasis." (PMID 33266506, 2020). "KLF4 significantly reduced the fraction of cells in S-phase, accompanied and eventually caused by upregulation of the bona fide KLF4 target gene p21, but also induced cleavage of PARP and caspase-3 indicating that KLF4 impaired tumor growth by inducing cell cycle arrest and apoptosis." (PMID 32944247, 2020). "In addition, an increased expression of the stem-like cell markers OCT4 and KLF4 was detectable at the edge of the tumor compared with the center." (PMID 32872409, 2020). "Besides, miR-7-5p has been validated to be down-regulated in CRC, and served as a tumor suppressor by targeting oncogene KLF4 in CRC." (PMID 32099527, 2020). "In addition, knockdown of KLF4 expression suppressed migration and invasion of CSCs as determined by real‐time tumour cell migration and invasion assays." (PMID 31830379, 2020). "Using this model, we demonstrate that the two highly aggressive PDX B-ALL models studied as well as several cell lines depend on downregulation of KLF4; reupregulating KLF4 using an inducible expression system or by treatment with Aza impairs tumor maintenance in vitro and in vivo." (PMID 32944247, 2020). "Introducing Aza into standard polychemotherapy protocols for B-ALL patients with the intention of raising KLF4 levels might reduce tumor burden and increase sensitivity to conventional chemotherapy." (PMID 32944247, 2020). "Many studies have shown that KLF4 plays a tumor-suppressive role in CRC." (PMID 33266506, 2020). "Given the disparate reports on the oncogenic/tumor-suppressive functions of KLF4 in breast epithelium, we first sought to confirm the previous findings on the impact of KLF4 on proliferation, migration, and invasion across multiple breast epithelial cell lines." (PMID 32552913, 2020). "Importantly, we have observed that depletion of KLF4 significantly boosts the efficacy of olaparib in suppressing 4T1 tumor progression." (PMID 33231937, 2020).